MAT1A (methionine adenosyltransferase 1A)
Description:
Catalyzes the formation of S-adenosylmethionine from methionine and ATP. The reaction comprises two steps that are both catalyzed by the same enzyme: formation of S-adenosylmethionine (AdoMet) and triphosphate, and subsequent hydrolysis of the triphosphate.
Synonyms: MAT-I/III; MATA1; MAT; SAMS; SAMS1
Tractability: Small molecule: it has a high-quality binding pocket. PROTAC: ubiquitination databases record sites on it.
Target class: Enzyme; Transferase
Gene: Protein-coding gene on chromosome 10 (80,269,780 to 80,290,126, reverse strand). Ensembl gene ENSG00000151224.
Subcellular location (Human Protein Atlas): Nucleoplasm; Cytosol
Pathways (Reactome):
Metabolism: Metabolism of ingested SeMet, Sec, MeSec into H2Se; Methylation; Sulfur amino acid metabolism
Disease: Defective MAT1A causes MATD
Gene Ontology:
Molecular function: identical protein binding; methionine adenosyltransferase activity; protein binding; ATP binding
Biological process: L-methionine catabolic process; protein homotetramerization; S-adenosylmethionine biosynthetic process; protein complex oligomerization
Cellular component: methionine adenosyltransferase complex; cytosol
Genetic constraint (gnomAD): Loss-of-function variants: 19 observed, 42.68 expected, observed/expected ratio (o/e) 0.45, 90% interval 0.31 to 0.65. The upper end of that interval is the gene's LOEUF score, 0.65, which puts it in group 2 of 6, group 1 being the genes least tolerant of losing a copy. Missense variants: 390 observed, 542.33 expected, observed/expected ratio (o/e) 0.72, 90% interval 0.66 to 0.78. Synonymous variants: 203 observed, 210.84 expected, observed/expected ratio (o/e) 0.96, 90% interval 0.86 to 1.08.
Gene-disease validity (ClinGen):
ClinGen rates the evidence that MAT1A causes each of these diseases.
methionine adenosyltransferase deficiency (autosomal recessive): Definitive. Hypermethioninemia due to methionine adenosyltransferase deficiency is a very rare metabolic disorder resulting in isolated hepatic hypermethioninemia that is usually benign due to partial inactivation of enzyme activity.
Homologues: Orthologues: chimpanzee MAT1A (100% identical), mouse Mat1a (96% identical), dog MAT1A (96% identical), rat Mat1a (96% identical), guinea pig MAT1A (94% identical), pig MAT1A (92% identical), macaque MAT1A (92% identical), tropical clawed frog mat1a (85% identical), zebrafish mat1a (82% identical), Drosophila melanogaster Sam-S (70% identical), Caenorhabditis elegans sams-3 (70% identical), Caenorhabditis elegans sams-5 (69% identical), and 2 more. Paralogues in human: MAT2A (84% identical).
Diseases named in the same sentence as MAT1A in open-access papers:
MAT1A is named in the same sentence as 56 diseases in open-access papers, as found by Europe PMC text mining. Sharing a sentence is not in itself a finding about the gene and the disease. The quoted sentences say what the papers report.
hepatocellular carcinoma (35 papers, 2011 to 2026). A malignant tumor that arises from hepatocytes. "Down-regulation of the liver-specific MAT1A gene encoding isozymes MATI/III and up-regulation of the MAT2A gene encoding isozyme MATII occur in hepatocellular carcinoma, and the resulting MAT1A: MAT2A switch leads to a decrease in SAM level." (PMID 33109235, 2020). "Development of liver cirrhosis and hepatocellular carcinoma (HCC) induces a switch in the expression of the isoenzymes in which MAT1A (encoding α1) expression is reduced and that of MAT2A increased." (PMID 23189196, 2012). "Indeed, Mat1a-deficient mice, which display hepatic SAM deficiency, are highly susceptible to liver cancer, whereas hepatoma cells transfected with MAT1A grow more slowly than control cells." (PMID 36979406, 2023). "Specifically, miR-485-3p was found to be upregulated in hepatocellular carcinoma, and to support tumor cell proliferation and survival in vitro and tumor growth and metastasis in mice by targeting the MAT1A gene, which encodes the α1 catalytic subunit of methionine adenosyltransferase." (PMID 35954369, 2022). "MAT1A, which maintains the differentiated state of hepatocytes, is downregulated in multiple liver diseases, during de-differentiation and in hepatocellular carcinoma." (PMID 38755480, 2024). "MAT1A knockout mice spontaneously develop macrovesicular steatosis and increased liver proliferation, which progresses to hepatocellular carcinoma." (PMID 38755480, 2024). "Increased PDRG1 expression is detected in acute liver injury and hepatoma cells, together with decreased MAT1A expression and nuclear accumulation of MATα1." (PMID 37240447, 2023). "Alterations of methionine cycle in steatohepatitis, cirrhosis, and hepatocellular carcinoma induce MAT1A decrease and MAT2A increase expressions with the consequent decrease of S-adenosyl-L-methionine (SAM)." (PMID 35159219, 2022). "Forced MAT1A overexpression in the liver carcinoma cell lines HepG2 and HuH7 results in a rise in SAM level, inhibits cell proliferation and induces apoptosis." (PMID 35159219, 2022). "Liver carcinogenesis is associated to a switch between MAT1A and MAT2A, with a consequent less efficient methionine metabolism, that enhances the capacity of hepatocytes and hepatoma cells to utilize nutrients for anabolic processes to support growth." (PMID 33207837, 2020). "Most of the hepatic diseases studied to date, including cirrhosis, hepatocellular carcinoma or acute liver injury, concur with a reduction in AdoMet concentrations due to a decrease in Mat1a expression and the concomitant increase in that of Mat2a and Mat2b." (PMID 27548429, 2016). "MAT1A knocked out mice develop oxidative stress and nonalcoholic steatohepatitis by 8 months and, a high incidence of hepatocellular carcinoma by 18 months." (PMID 26289392, 2015). "miR-664 has a potential tumor suppressive activity in hepatocellular carcinoma and has been documented to downregulate methionine adenosyltransferase 1A (MAT1A)." (PMID 25174825, 2014). "Furthermore, we found significant differences in clinicopathological characteristics (age, gender, fibrosis Ishak score, pathologic T, and race) between HSPA1A, NR1I3, PPARGC1A, and MAT1A gene expressions and hepatocellular carcinoma patients." (PMID 37993485, 2023). "Natively, MAT1A has a tissue specific expression pattern with robust expression in liver, pancreas, skin, ovaries, and testis tissues and has been previously characterized in the context of hepatocellular carcinoma." (PMID 31600961, 2019). "Interestingly, forced expression of MAT1A in human hepatoma cells suppresses in vivo tumorigenicity in mice." (PMID 31234428, 2019). "Human hepatoma cell line Huh7 was stably transfected with MAT1A expression vector." (PMID 24212770, 2011).
hepatocellular carcinoma (continued). "In cancer research, MAT1A has been mostly described in the context of hepatocellular carcinoma (HCC), where it was previously shown that a switch in gene expression from MAT1A to MAT2A (M1-M2 switch) promoted cancer invasion and metastasis." (PMID 31600961, 2019). "Therefore, the changes induced in hepatoma cells by Pdrg1 downregulation seem to follow an opposite pattern than those exhibited by Mat1a-/- or Gnmt-/- livers with hepatic damage (esteatosis, hepatocellular carcinoma), which show induced or normal lipogenesis, respectively." (PMID 27548429, 2016). "In hepatocellular carcinoma (HCC), MAT1A downregulation and MAT2A upregulation occur, known as the MAT1A:MAT2A switch." (PMID 24098708, 2013). "Furthermore, reduced MAT1A expression has been correlated with poor prognosis in hepatocellular carcinoma (HCC), suggesting its potential as a prognostic biomarker." (PMID 39438468, 2024). "To investigate the impacts of MAT1A and GNMT expression on human hepatoma cells, we utilized cell models that expressed various levels of these 2 genes." (PMID 35008908, 2022). "LINC00662 can trigger malignant progression as a competing endogenous RNA by sponging different miRNAs or altering genomic methylation profiles by binding to the mRNA of MAT1A and the ACHY protein in hepatocellular carcinoma." (PMID 34148056, 2021). "In hepatocellular carcinoma, SNHG6 lowers DNA methylation through inhibition of S-adenosylmethionine and down-regulation of MAT1A (methionine adenosyltransferase 1A)." (PMID 32318335, 2020). "In hepatocellular carcinoma (HCC), the down-regulation of MAT1A gene and the up-regulation of MAT2A occur, known as the MAT1A:MAT2A switch." (PMID 24098708, 2013). "Fall in MAT1A expression and MATI/III activity with concomitant up-regulation of MAT2A occurs in hepatoma cell lines and rodent HCC as well as in human liver cirrhosis and HCC." (PMID 24212770, 2011). "In hepatocellular carcinoma (HCC) and cholangiocarcinoma (CCA), MAT1A expression is reduced, and the induction of FOXM1 and NF-κB expression is accompanied by a decrease in MATα1 (the protein encoded by MAT1A) expression, while MATα1 positively regulates the expression of p50 and p65." (PMID 41513616, 2026). "Moreover, Mat1a-KO mice spontaneously develop NAFLD with age; NASH at 8-month-old, which progresses to hepatocellular carcinoma (HCC) at 16-month-old6,42." (PMID 35232994, 2022). "Interestingly, repression of Mat1a with the induction of Mat2a, which is usually only expressed during liver development, is characteristic of NAFLD and aggressive hepatocellular carcinoma progression." (PMID 32908189, 2020). "Our analysis of The Cancer Genome Atlas (TCGA) human Liver Hepatocellular Carcinoma (LIHC) dataset confirmed that key genes involved in SAA metabolism, including MAT1A, BHMT, CBS, CTH, and CDO1, are suppressed in HCC compared to normal liver." (PMID 32770044, 2020). "Interestingly, many enzymes involved in SAA metabolism, including MAT1A, GNMT, BHMT, and CBS, are reported to be downregulated in human liver tumors, particularly hepatocellular carcinoma (HCC), the most common and deadly form of liver cancer." (PMID 32770044, 2020).
liver cancer (18 papers, 2011 to 2025). An epithelial or non-epithelial malignant neoplasm that arises from the liver. "Another mechanism by which SAMe deficiency can promote HCC development in Mat1a KO mice is constituted by the increase of hepatic cancer stem cells." (PMID 39941901, 2025). "In particular, the loss of Mat1a induces a drastic reduction in liver SAMe levels, the spontaneous appearance of hepatic steatosis, and its progression to steatohepatitis, fibrosis, and ultimately liver cancer." (PMID 37123053, 2022). "Alternatively, strategies forcing the expression of MAT1A in liver cancer, instead of directly treating with SAMe, were shown to reduce HCC growth and angiogenesis, and increase apoptosis in in vitro and in vivo models." (PMID 39941901, 2025). "To identify liver cancer suppressor genes related to liver-TE that are controlled by KDM1A-mediated HNF4A repression, we focused on MAT1A, a known HNF4A target gene associated with liver-TE which is directly repressed by KDM1A." (PMID 38965210, 2024). "MAT1A is often silenced in human liver cancer and overexpression of MAT1A in liver cancer cells resulted in higher SAMe level and increased apoptosis." (PMID 26416353, 2015). "Our recent findings have shown that MAT1A KO mice have expansion of a population of oval cells that behave like liver cancer stem cells as they age." (PMID 24212770, 2011). "We have demonstrated that MAT1A expression in liver cancer cells can reduce cell proliferation, invasion of the cell model (through a decrease in the translation-related gene), and eukaryotic translation elongation (EEF1D), and that MAT1A expression can predict a better prognosis in human LIHC." (PMID 37240447, 2023). "MAT1A loss results in reduced SAM synthesis, which is a feature of both cirrhosis and HCC that leads to global hypomethylation in rat livers during hepatocarcinogenesis, and is associated with increased proliferation in human liver cancer cells." (PMID 34863035, 2022). "It has been found that crosstalk between FOXM1/NF‐κB and MAT1A (methionine adenosyl transferase 1A) may affect tumorigenesis in liver cancer, but little is known about MAT1A in GBC." (PMID 33718182, 2021). "The decrease in MAT1A gene expression with a consequent reduction of the MATI and MATIII isoenzymes leads to a marked fall of SAM liver content during acute and chronic liver disease, which predisposes the subject to the development of liver cancer." (PMID 31234428, 2019). "Further work has shown that liver cancer stem cells from MAT1A KO mice possess highly enhanced mitogen-activated protein kinase (MAPK) signaling with increased level and activity of the extracellular signal regulated kinase (ERK), known to be associated strongly with HCC development." (PMID 24212770, 2011). "By 18 months of age, many of the MAT1A KO mice developed liver cancer." (PMID 24212770, 2011). "First is the existence of liver cancer stem cell population in the aging MAT1A KO mice." (PMID 24212770, 2011). "Switching from MAT1A to MAT2A expression could contribute to the development of liver cancer." (PMID 26418898, 2016). "In liver cancers, including HCC and cholangiocarcinoma, MAT1A expression and activity has been found to be reduced correlating with depletion of SAMe levels, promoter methylation status and, also, associates with MAT2A induction." (PMID 39941901, 2025). "Livers of MAT1A-KO mice become depleted of reduced glutathione and spontaneously develop fibrosing NASH and liver cancer." (PMID 36535507, 2022). "As mentioned in the literature, a switch in gene expression from MAT1A to MAT2A, known as the MAT1A:MAT2A switch, has been found in liver cancer." (PMID 24098708, 2013). "Pan-cancer expression profiling showed that MAT1A is liver tissue-specific, highly expressed in normal liver and liver cancer tissues, but downregulated in liver cancers compared to normal liver tissues, a pattern exemplifies HNF4A downstream signature." (PMID 38965210, 2024).
steatosis (13 papers, 2011 to 2025). Increased lipid within the cytoplasm of cells. "Consistently, upon WD challenge, hepatic MAT1A deficient mice showed worsened steatosis and higher liver injury." (PMID 36171419, 2022). "Indeed, when challenged with WD, hepatic MAT1A deficient mice accumulated ~40% more TG, ~60% more cholesterol and showed worsened steatosis than controls." (PMID 36171419, 2022). "Methionine adenosyltransferase 1a-KO mice (Mat1a-KO) are characterized by hepatic SAMe deficiency and intragastric ethanol-fed mice are marked by an increased susceptibility to steatosis and oxidative liver injury, spontaneous development of steatohepatitis and HCC." (PMID 22166123, 2011). "Reportedly, MAT1A−/− mice can spontaneously develop steatosis, exhibiting reduced SOD activity and heightened lipid peroxidation, thereby accelerating the progression of NAFLD to NASH." (PMID 41567634, 2025). "Deletion of Mat1a in mice fed a normal diet leads to the spontaneous development of steatosis that progresses to NASH, fibrosis, and eventually hepatocellular carcnoma." (PMID 37123053, 2022). "In this model, steatosis and inflammation occurred in the liver and Mat1a mRNA levels were upregulated." (PMID 35091576, 2022). "Mice lacking Mat1a (Mat1a-KO) exhibit chronically reduced hepatic SAMe levels, are more susceptible to steatosis and liver injury, and spontaneously develop steatohepatitis and HCC." (PMID 41462685, 2025). "Mice with Mat1a gene deletion (Mat1a knockout mice) have increased hepatic weight compared to WT animals under a normal chow diet, while at eight months of age, they develop spontaneous macrovesicular steatosis and predominantly periportal mononuclear cell infiltration, signs of NASH." (PMID 36555433, 2022). "Despite the absence of steatosis under chow diet condition, there is an overall trend of elevated hepatic medium chain acylcarnitines and significantly decreased β-hydroxybutyrate, suggesting that hepatic MAT1A deficiency is associated with reduced hepatic fatty acid oxidation." (PMID 36171419, 2022). "Similar alterations have been described in MATO-KO mice, a NASH-HCC animal model that in the absence of Mat1a cannot synthesize SAM and presents steatosis involving 25–50% of hepatocytes and mononuclear cell infiltration in periportal areas, at eight months, and HCC at 18 months of age." (PMID 35159219, 2022).
liver disease (11 papers, 2014 to 2025). "Dysregulation of BHMT2 and MAT1A has been implicated in various pathological conditions, such as liver diseases and cancer." (PMID 41219226, 2025). "Keywords included “alcohol-associated liver disease,” “alcoholic liver disease,” “methionine metabolism,” “SAMe,” “MAT1A,” “oxidative stress,” “mitochondrial dysfunction,” “fibrosis,” “epigenetics,” and related terms." (PMID 41462685, 2025). "Lastly, we observed that MCJ is upregulated in alcohol-associated liver disease, a condition characterized by reduced MAT1A expression and SAMe levels along with mitochondrial injury." (PMID 38385082, 2024). "A shift from MAT1A to MAT2A/MAT2B is observed in multiple liver diseases, indicating its involvement in liver growth and dedifferentiation." (PMID 40034261, 2025). "During human liver growth, multiple liver diseases, and de-differentiation, MAT1A switches to MAT2A/MAT2B, which will decrease the hepatic SAM level." (PMID 37240447, 2023). "Reduced MAT1A gene expression and enzyme isoform switching restrict SAMe synthesis in some liver diseases of humans and in rodent models." (PMID 34820906, 2022). "The results obtained to date using models of hepatic disease show that altered concentrations of this metabolite commonly derive from the Mat1a/Mat2a expression switch, and post-translational modifications on cytosolic MATα1 induced by nitrosative and oxidative stress." (PMID 27548429, 2016). "This suggests that alcohol plays a role in a feedback loop that propagates the DNA hypomethylation phenotype, consistent with previous reports that MAT1A, which catalyzes the formation of SAM by linking methionine and ATP, is downregulated in liver disease leading to decreased SAM levels." (PMID 25294808, 2014).
Cirrhosis (10 papers, 2008 to 2025). A chronic disorder of the liver in which liver tissue becomes scarred and is partially replaced by regenerative nodules and fibrotic tissue resulting in loss of liver function. "MAT1A gene down-regulation at the transcriptional level, in alcoholic hepatitis, cirrhosis and HCC, largely depends on MAT1A promoter methylation and histone H4 deacetylation and on MAT1A mRNA interaction with AUF1 protein, which enhances its decay." (PMID 31073374, 2019). "This molecular event (MAT1A/MAT2A switch) is responsible for the decrease in SAM/SAH (S-adenosylhomocysteine) ratio in cirrhosis and HCC." (PMID 31073374, 2019). "MAT1A deficiency lowers SAM levels and predisposes individuals to MASLD‐associated HCC, while MAT1 promoter hypermethylation has been linked to hyperhomocysteinemia in cirrhosis." (PMID 40693828, 2025). "The MAT1a knockout mouse develops steatohepatitis, cirrhosis, and HCC." (PMID 35008267, 2021). "MAT1A gene is specifically silenced by hypermethylation in human cirrhosis, which leads to a marked reduction of SAMe synthesis, We discovered the SAMe content could be decreased by knocking down MAT2A and increased by knocking down MAT2β which were in agreement with the results of Komal." (PMID 19025580, 2008). "In patients with cirrhosis and HCC, the level of methionine adenosyltransferase (MAT1A), a crucial gene involved in the methionine metabolism, is downregulated, thereby leading to hypermethioninemia and reduced hepatic glutathione concentrations." (PMID 31590436, 2019). "Chronic hepatitis and cirrhosis and HCC of rodents and humans are characterized by a fall in MAT1A expression and a rise in MAT2A expression, with consequent decrease of MAT1A: MAT2A ratio (an event referred to as “MAT1A/MAT2A switch”)." (PMID 31569678, 2019).